TRPM5 (transient receptor potential cation channel subfamily M member 5)
Description:
Monovalent cation-selective ion channel activated by intracellular Ca(2+) in a voltage- and temperature-dependent manner. Mediates the transport of Na(+), K(+) and Cs(+) ions equally well. Activated directly by increase in intracellular Ca(2+), but is impermeable to it. The activation mechanism of TRPM5 involves a multistep process. TRPM5 activation involves ligand binding (i.e., tastant molecule, glucose stimulation) to Gq/G protein-coupled receptors (GPCR) and leads to the breakdown of phosphatidylinositol bisphosphate (PIP2) into diacylglycerol (DAG) and inositol trisphosphate (IP3), IP3 binds to its receptors in the endoplasmic reticulum and cause calcium release. Simultaneously with the intracellular Ca(2+) release, DAG activates the protein kinase C (PKC), which phosphorylates the TRPM5 channel. This phosphorylation combined with the bound Ca(2+), leads to a robust inward current allowing the entry of sodium ions (Na+) into the cell. This ion influx depolarizes the cell membrane, generating action potentials that propagate TRPM5 signals. Is a key player in sensing sweet, umami and bitter stimuli (By similarity). Involved in insulin secretion by pancreatic beta cells (By similarity).
Synonyms: LTrpC5; MTR1
Tractability: Small molecule: a high-quality ligand is known; it belongs to a druggable protein family. Antibody: its Gene Ontology location is reachable by antibodies, with high confidence; UniProt places it where antibodies can reach, with medium confidence; UniProt predicts a signal peptide or a membrane-spanning region. PROTAC: a small molecule that binds it is known.
Target class: Voltage-gated ion channel; Ion channel; Transient receptor potential channel
Gene: Protein-coding gene on chromosome 11 (2,404,515 to 2,444,514, reverse strand). Ensembl gene ENSG00000070985.
Subcellular location: Cell membrane
Pathways (Reactome):
Sensory Perception: Sensory perception of sweet, bitter, and umami (glutamate) taste
Transport of small molecules: TRP channels
Gene Ontology:
Molecular function: calcium-activated cation channel activity; monoatomic ion channel activity; protein binding; sodium channel activity; calcium ion binding; identical protein binding; potassium channel activity
Biological process: calcium ion transmembrane transport; metal ion transport; monoatomic cation transmembrane transport; monoatomic ion transport; positive regulation of insulin secretion involved in cellular response to glucose stimulus; potassium ion transmembrane transport; sodium ion transmembrane transport; transmembrane transport
Cellular component: membrane; plasma membrane; dendrite; neuronal cell body
Genetic constraint (gnomAD): Loss-of-function variants: 122 observed, 105.45 expected, observed/expected ratio (o/e) 1.16, 90% interval 1 to 1.35. The synonymous counts are far from expectation, so gnomAD's model fits this gene poorly and the ratio says little. Missense variants: 1,641 observed, 1,474.2 expected, observed/expected ratio (o/e) 1.11, 90% interval 1.07 to 1.16. Synonymous variants: 781 observed, 644.54 expected, observed/expected ratio (o/e) 1.21, 90% interval 1.14 to 1.28.
Homologues: Orthologues: chimpanzee TRPM5 (99% identical), macaque TRPM5 (94% identical), guinea pig TRPM5 (84% identical), mouse Trpm5 (84% identical), pig TRPM5 (83% identical), rat Trpm5 (83% identical), dog TRPM5 (82% identical), zebrafish trpm5 (57% identical), Caenorhabditis elegans gon-2 (26% identical), Drosophila melanogaster Trpm (26% identical), Caenorhabditis elegans ced-11 (17% identical), Caenorhabditis elegans trpl-2 (11% identical), and 2 more. Paralogues in human: TRPM4 (44% identical), TRPM2 (38% identical), TRPM8 (30% identical), TRPM1 (28% identical), TRPM3 (28% identical), TRPM6 (27% identical), TRPM7 (27% identical).
Diseases named in the same sentence as TRPM5 in open-access papers:
TRPM5 is named in the same sentence as 48 diseases in open-access papers, as found by Europe PMC text mining. Sharing a sentence is not in itself a finding about the gene and the disease. The quoted sentences say what the papers report.
melanoma (10 papers, 2017 to 2025). A malignant, usually aggressive tumor composed of atypical, neoplastic melanocytes. "TRPM5 expression is closely associated with prognosis in patients with malignant melanoma as increased levels are indicative of poor prognosis and highly aggressive melanoma." (PMID 37445615, 2023). "High TRPM5 mRNA expression has been associated with poor OS in both gastric cancer and melanoma patients." (PMID 38188686, 2023). "In contrast, Trpm5 mRNA, which encodes a molecule involved in sensing acidic pHe and whose overexpression in patients with melanoma and gastric cancer has been associated with shorter survival, was not affected by transient acidification." (PMID 31489536, 2020). "High TRPM5 expression is associated with lower overall survival (OS) in melanoma patients." (PMID 39633507, 2024). "High TRPM5 expression in melanoma patients was associated with shorter survival time." (PMID 29108231, 2017). "Analysis in silico also suggested a significant correlation between high levels of TRPM5 expression and shorter survival in patients with melanoma and gastric cancer." (PMID 37894842, 2023). "In silencing TRPM5 B16 melanoma cells, these authors observed a reduction of MMP-9 expression, a hallmark of solid tumors associated with EMT, induced by the acidic extracellular pH." (PMID 36844925, 2022). "In conclusion, this study is the first to show that TRPM5 is associated with acidic pHe-signaling in Mmp9 mRNA expression in B16-BL6 melanoma cells and that pharmacological inhibition of TRPM5 successfully inhibited their spontaneous metastasis." (PMID 29108231, 2017). "TRPM5 is conducive to the metastasis of mouse melanoma cells." (PMID 39633507, 2024). "TRPM5 protein is highly expressed in BL6 cells, a metastatic B16 melanoma variant." (PMID 36844925, 2022). "Similarly, in murine B16-BL6 melanoma cells, TRPM5 mediated acidic extracellular-pH signalling, whereas TRPM5 inhibition reduced spontaneous metastasis in these cells." (PMID 36046118, 2021). "The present study assessed whether TRPM5, an intracellular Ca2+-dependent monovalent cation channel, is associated with acidic pHe signaling and induction of MMP-9 expression in this mouse melanoma model." (PMID 29108231, 2017). "We further checked whether TRPM5 expression predicts clinical outcome for human melanoma patients." (PMID 29108231, 2017). "Finally, TRPM5 was targeted in melanoma bearing mice by treatment with TPPO." (PMID 29108231, 2017). "As previously discussed, other members of the TRPM subfamily (TRPM1, TRPM5, TRPM7, and TRPM8) appear to have essential roles in melanoma." (PMID 37445615, 2023). "The role of TRPM5 channels has been shown in lung cancer, TRPM1 in melanoma, and TRPM4 channel in prostate cancer as well." (PMID 29875336, 2018). "An in vitro study on mouse melanoma cells found that triphenylphosphine oxide (TPPO), a selective TRPM5 blocker, dose-dependently inhibited acidic pHe-induced matrix metalloproteinase-9 (MMP-9) production (IC50: 41 mM after 24 h), but did not reduce cell viability." (PMID 40227837, 2025). "In the same study, in silico analysis showed a significant correlation between high levels of TRPM5 expression and shorter overall survival in patients with melanoma and gastric cancer, but not with lung, breast, and rectum cancers." (PMID 40227837, 2025). "TRPM5 may rely on its ability to transport K+ to amplify extracellular acidic signaling and enhance acidic pH-induced MMP-9 expression to promote melanoma lung metastasis." (PMID 39633507, 2024). "In silico analysis of clinical samples showed that high TRPM5 mRNA expression correlated with poor overall survival rate in patients with melanoma and gastric cancer but not in patients with cancers of the ovary, lung, breast, and rectum." (PMID 29108231, 2017).
melanoma (continued). "In contrast to our findings in OAC, high TRPM5-mRNA expression correlated with poor overall survival in patients with melanoma and gastric cancer; high TRPM5-expression did not, however, correlate with poor, overall survival in patients with ovarian, lung, breast, or rectal cancer." (PMID 36046118, 2021). "That study, however, did not analyze TRPM5 expression in melanoma and gastric cancer." (PMID 29108231, 2017). "In addition, in silico analysis showed a significant correlation between high levels of TRPM5 expression and shorter overall survival in patients with melanoma and gastric cancer, but not in patients with cancers of the lung, breast, and rectum." (PMID 29108231, 2017).
type 2 diabetes (10 papers, 2011 to 2023). "Perhaps in patients with type 2 diabetes, umami, sweet and bitter taste dysfunctions are associated with decreased TRPM5 expression." (PMID 36198698, 2022). "In humans, genetic variation in TRPM5 has been reported to be likely associated with pre-diabetic phenotypes and contribute to the development of type 2 diabetes mellitus." (PMID 24886386, 2014). "SLC2A7_rs7699022 and TRPM5_rs1965606 had a significant association with type 2 diabetes." (PMID 32724612, 2020). "Besides TRPA1, TRPM5 is also often associated with type II diabetes." (PMID 30087301, 2018). "The glucose intolerant phenotype of the TRPM5 (−/−) mouse implies a role for aberrant TRPM5 activity in the pathomechanism of type-2 diabetes." (PMID 37240443, 2023). "Our data show that stevioside has potent therapeutic effects for the prevention and treatment of type 2 diabetes in mice, and we show that the molecular mechanism of these effects is the potentiation of TRPM5 activity in β-cells." (PMID 28361903, 2017). "As TRPM5 appears to be involved in glucose-dependent insulin secretion, TRPM5 dysfunction has been suggested to be a factor in the etiology of some forms of type 2 diabetes." (PMID 21420431, 2011). "This functional implication is corroborated by the finding that the expression of TRPM5 in the upper small intestine is inversely correlated with the blood glucose concentration in type 2 diabetes patients." (PMID 21420431, 2011). "Therefore, stevioside, as TRPM5 modulator, is a promising therapeutic option in type II diabetes patients." (PMID 30087301, 2018). "TRPM5 plays a major role in glucose‐induced insulin secretion beyond membrane depolarization, and its dysfunction may lead to the occurrence and development of type 2 diabetes." (PMID 38107122, 2023). "Glucose-induced insulin secretion is decreased and glucose tolerance is impaired in Trpm5−/− mice, while activation of TRPM5 may stimulate the pancreatic β-cells to secrete insulin, preventing the onset of diabetes mellitus type II." (PMID 33525598, 2021).
diabetes (6 papers, 2014 to 2023). "Dysfunction of the TRPM5 channel has been linked to a range of disease states, including diabetes, intestinal infections, and inflammatory responses." (PMID 38188686, 2023). "Our results showed that the expression of STRs and associated signaling components (Gα-gustducin, PLCβ2, and TRPM5) was obviously downregulated under the condition of diabetes in vivo and in vitro." (PMID 29675433, 2018). "The most significantly downregulated gene associated with insulin secretion and diabetes in WFS1‐deficient islets following Wfs1 was melastatin‐related transient receptor potential subfamily member 5 (Trpm5)." (PMID 27053292, 2016). "Further studies are needed to verify the functional interaction between WFS1 and TRPM5 in the regulation of insulin secretion and how this downregulation may contribute to diabetes‐like phenotype of WFS1‐deficient mice." (PMID 27053292, 2016). "In addition, we also found that TRP ion channel family genes (TRPV4, TRPV1, TRPM4, and TRPM5) related to obesity or diabetes were highly expressed in HBV-related HCC." (PMID 34512754, 2021).
gastric cancer (6 papers, 2017 to 2023). A primary or metastatic malignant neoplasm involving the stomach. "The present study showed that overall survival of gastric cancer patients was significantly shorter in patients with high than low levels of TRPM5." (PMID 29108231, 2017). "Likewise, further investigations have reported that elevated expression of TRPM5 was related to lower survival in patients suffering from gastric cancer." (PMID 37337283, 2023). "However, additional research are required to confirm the significance of TRPM2 and TRPM5 in the survival and clinical outcomes of patients with gastric cancer." (PMID 37337283, 2023).
colonic cancer (5 papers, 2013 to 2023). "To further explore the mechanism underlying the chemoresistance associated with TRPM5 gene for colon cancer, we unveiled a positive correlation between the expression of TRPM5 and the multi-drug resistance gene, MDR1." (PMID 38188686, 2023). "Secondly, although we have uncovered an association between TRPM5 levels and chemotherapy resistance in colon cancer, the specific mechanisms remain to be explored experimentally." (PMID 38188686, 2023). "Furthermore, we have identified TRPM5 as a pivotal hub gene associated with chemoresistance, offering potential as a molecular target for overcoming chemoresistance in colon cancer patients." (PMID 38188686, 2023). "In summary, our study is the first to introduce a novel three-gene signature based on TRP channel-related genes, shedding light on the potential of TRPM5 as a target for combatting chemoresistance in colon cancer." (PMID 38188686, 2023). "The signature we constructed consists of three genes (MCOLN1, TRPM5, and TRPV4), all identified as independent prognostic and risk factors for colon cancer through the multivariate Cox regression model." (PMID 38188686, 2023). "IRG signature of AXIN2, CCL22, CLEC10A, CRIP2, RUNX3, and TRPM5 is a reliable prognostic predictor for colon cancer patients." (PMID 33401247, 2020). "In human colonic cancer cells (HT29-18N2), TRPM5 channels have the potential as pharmacological targets for managing mucus-associated pathologies, such as cystic fibrosis, given their roles in regulating Ca2+-mediated mucin 2 and MUC5AC secretion." (PMID 38188686, 2023). "siRNA-mediated knockdown of 7343 human gene products in a human colonic cancer goblet cell line (HT29-18N2) revealed new proteins, including a Ca2+-activated channel TRPM5, for MUC5AC secretion." (PMID 23741618, 2013).
Obesity (4 papers, 2015 to 2023). Accumulation of substantial excess body fat. "Trpm5−/− mice maintain normal weight with a carbohydrate-rich diet and consume less alcohol, indicating the importance of TRPM5 antagonists in obesity and/or alcohol use disorders." (PMID 37569884, 2023). "In the current study TRPM5 was found to be modulated by obesity in trachea and duodenum, as well as in the brainstem." (PMID 27388805, 2016). "The aim of this study was to investigate the effects of TRPM5 gene ablation on body weight, insulin sensitivity and other metabolic parameters in long-term high caloric diet induced obesity." (PMID 26397098, 2015). "The aim of the present study was to investigate the role of TRPM5 gene ablation on body weight, insulin sensitivity and other metabolic parameters in long-term high caloric diet induced obesity." (PMID 26397098, 2015). "In brief, we have showed that Trpm5-/- mice gained significantly less body weight and fat mass on both palatable carbohydrate rich cafeteria diet and 60% HFD and were more glucose tolerant compared to wild type mice, which after cafeteria diet induced obesity was largely independent of body weight." (PMID 26397098, 2015).
lung carcinoma (3 papers, 2018 to 2025). "The exposure to a transient extracellular acidification slightly altered the mRNA expression of Trpm5 in the LLCm1 lung cancer cell line, differently from chronic exposure that induced a high expression of the channel." (PMID 40227837, 2025).
Cirrhosis (2 papers, 2016 to 2021). A chronic disorder of the liver in which liver tissue becomes scarred and is partially replaced by regenerative nodules and fibrotic tissue resulting in loss of liver function. "The present study investigates the association of TRPM5 rs886277 polymorphism with liver fibrosis progression and cirrhosis development in chronic hepatitis C (CHC) patients." (PMID 33525598, 2021). "TRPM5 rs886277 polymorphism was associated with liver fibrosis progression and cirrhosis development among HCV-infected patients." (PMID 33525598, 2021). "The present study’s objective was to investigate the association of TRPM5 rs886277 polymorphism with liver fibrosis progression and cirrhosis development in CHC patients." (PMID 33525598, 2021). "This study focused on the impact of TRPM5 rs886277 polymorphism on liver fibrosis progression and cirrhosis." (PMID 33525598, 2021). "Specifically, the TRPM5 rs886277 C allele and CC genotype were risk factors in the progression of liver fibrosis and cirrhosis compared to the TRPM5 rs886277 T allele and TT/CT genotype, respectively." (PMID 33525598, 2021). "TRPM5 rs886277 polymorphism is a missense variant (Asn235Ser) in exon 5, which could generate a protein with altered expression or channel functions, causing an increase in intracellular Ca2+ and hepatotoxicity, resulting in hepatic scarring and cirrhosis." (PMID 33525598, 2021). "The TRPM5 rs886277 polymorphism is a missense (Asn235Ser) variant related to liver fibrosis in HCV-infected patients, primarily as part of the cirrhosis risk score (CRS), which comprised seven SNPs predictive of fibrosis progression in HCV-infected patients and liver transplantation." (PMID 33525598, 2021). "Moreover, a cirrhosis risk score consisting of SNPs in 7 genes (AP3S2, AQP2, AZIN1, DEGS1, STXBP5L, TLR4, and TRPM5) has been shown to predict fibrosis progression in HCV infected patients." (PMID 26950933, 2016).
colon adenocarcinoma (2 papers, 2023 to 2025). "The findings unveiled a novel three TRP channels-related gene signature (MCOLN1, TRPM5, and TRPV4) in colon adenocarcinoma (COAD)." (PMID 38188686, 2023).
cystic fibrosis (2 papers, 2022 to 2023). Autosomal recessive disorder caused by pathogenic variants in the CFTR gene (cystic fibrosis transmembrane conductance regulator), which encodes a chloride and bicarbonate channel expressed in epithelial cells, and follow the diagnosis criteria. "Four hours after infection with the P. aeruginosa cystic fibrosis isolate NH57388A, the number of the recruited neutrophils in the tracheae of WT mice was significantly higher than in Trpm5–/– mice." (PMID 35503420, 2022).
helminth infection (2 papers, 2021 to 2023). "TCs express choline acetyltransferase for acetylcholine (ACh) synthesis, leading to the activation of Trpm5 during helminth infection." (PMID 38283340, 2023). "These Trpm5-expressing TCs are responsible for helminth infection in the gut." (PMID 38283340, 2023).
hyperglycaemia (2 papers, 2017 to 2023). "SGs modulate taste responses and insulin release by activating TRPM5 (Transient receptor potential cation channel subfamily M member 5) ion channel, and the potentiation of TRPM5 activity protects mice against the development of high-fat diet induced hyperglycaemia." (PMID 36745615, 2023).
Hypertension (2 papers, 2020 to 2024). The presence of chronic increased pressure in the systemic arterial system. "Even long-term BME intake significantly improved aversion to high salt concentrations by upregulating TRPM5 expression and function, ultimately decreased excessive salt intake in mice and improved cardiovascular dysfunction induced by high salt and hypertension angiotensin II-induced." (PMID 33291725, 2020). "Lastly, the same group demonstrated that by increasing the expression of TRPM5 in mice through the injection of bitter melon extract (BME) and cucurbitacin E (CuE), a major compound in BME, high salt-induced hypertension was reduced." (PMID 33291725, 2020).